VCAN (versican)
Diseases named in the same sentence as VCAN in open-access papers (continued):
Sharing a sentence is not in itself a finding about the gene and the disease.
melanoma (26 papers, 2007 to 2024). A malignant, usually aggressive tumor composed of atypical, neoplastic melanocytes. "Versican expression is associated with a proliferative cell phenotype and is often found in tissues that show high proliferation, such as embryonic tissues, and in a variety of tumors, including breast, brain, prostate, and melanoma." (PMID 36338393, 2022). "These include increased expression of CSPG4 and CHST15 in melanoma cells, as well as increased expression of versican in prostate epithelial cells, of Wnt9A in colonic epithelial cells, and of HIF-1α in bronchial and colonic epithelial cells." (PMID 38892038, 2024). "Tumor volume and weight measurements showed that DSE overexpression significantly inhibited melanoma growth, while VCAN knockdown reversed the inhibitory effect of DSE on melanoma." (PMID 37833287, 2023). "In terms of mechanism, DSE inhibits the progression of melanoma by regulating the intratumoral invasion of anti-tumor immune cells and the expression of VCAN." (PMID 37833287, 2023). "DSE overexpression significantly inhibited the proliferation of melanoma cells, while VCAN knockdown inhibited the effect of DSE overexpression." (PMID 37833287, 2023). "In terms of mechanism, DSE inhibits the progression of melanoma by regulating the intratumoral invasion of anti-tumor immune cells and the expression of Versican (VCAN)." (PMID 37833287, 2023). "Mechanistically, DSE promoted the expression of VCAN, which inhibited the biological activity of melanoma cells." (PMID 37833287, 2023). "Knockdown of VCAN expression in DSE-overexpressed melanoma A2508 cells eliminated the tumor suppressive effect of DSE." (PMID 37833287, 2023). "Together, these results suggest that DSE is downregulated in melanoma tissues, and that high expression of DSE can promote melanoma progression by inducing immune cell infiltration and VCAN expression." (PMID 37833287, 2023). "Versican, encoded by the Vcan gene, was reported to impact the accumulation of MDSCs, and silencing Versican promoted the anti-tumor efficacy of endostatin in a B16F1 melanoma tumor model." (PMID 32290071, 2020). "Silencing of versican increases cell proliferation and migration, whereas silencing of fibronectin increases drug sensitivity of melanoma cells." (PMID 27184066, 2016). "Pharmacological inhibition of MEK1 and MEK2 inhibits versican expression in melanoma cells." (PMID 39400584, 2024). "In addition, by injecting melanoma cells into the caudal vein of nude mice to construct a tumor lung metastasis model, we also found that VCAN knockdown eliminated DSE-inhibited melanoma lung metastasis." (PMID 37833287, 2023). "In addition, our results suggest that DSE regulates the progression of melanoma by regulating the expression of VCAN." (PMID 37833287, 2023). "Moreover, VCAN knockdown also significantly eliminated the inhibitory effect of DSE on melanoma invasion and migration." (PMID 37833287, 2023). "CSPG4 is not the only proteoglycan with C4S attachments, and other chondroitin sulfate proteoglycans, such as versican, may also be increased in the melanoma cells." (PMID 27926479, 2017). "Given the requirement of Adamts20 for Kit signaling and versican cleavage, it is intriguing to consider how dysregulation of signaling between ADAMTS20, Kit, and versican might contribute to melanoma progression." (PMID 18454205, 2008). "However, we provide evidence that VCAN may perform the opposite function in melanoma cells." (PMID 37833287, 2023). "The correlation between DSE and VCAN expression in melanoma tissues was analyzed by immunofluorescence staining, and a significant positive correlation was found between DSE expression and VCAN expression." (PMID 37833287, 2023). "For example, in melanoma, resistance against BRAF-inhibitor was accompanied by increased ECM levels of versican and biglycan." (PMID 33330449, 2020).
melanoma (continued). "Among the most interesting, highly and significantly over-expressed genes in metastatic primary melanomas were TIMP1, VCAN, SPP1, and CTHRC1, all of which are expressed both by stromal fibroblasts and melanoma cells (data not shown)." (PMID 26918341, 2016). "Downregulation of these genes by CtBP1 was confirmed by transient transfection of CtBP1 into the melanoma cell line (Col1A2: 0.31, FAT: 0.52, SLC26A2: 0.72, VCAN: 0.75 compared to mock control set as 1)." (PMID 19216735, 2009). "VCAN expression is elevated in our invasive Motif 1 NZM cells, which is in agreement with a recent report that VCAN is up-regulated in invasive human melanoma cells via a TCF4/AP1-mediated mechanism." (PMID 20041153, 2009). "In another cancer model, SK-mel-131 melanoma cells, transcriptional regulation of versican is controlled by the c-jun N-terminal kinase (JNK) pathway, in which c-jun binds to an AP-1 site on the versican promoter." (PMID 39400584, 2024). "The epigenetic mechanism in the melanoma cells affecting PD-L1 expression resembles the previously observed mechanisms by which ARSB and chondroitin 4-sulfation affect galectin-3 and AP-1, as shown by transcriptional effects on HIF-1α, Wnt9a, and versican." (PMID 38892038, 2024). "Interestingly, VERSICAN and KITL overexpression are observed in primary melanomas and levels correlate with melanoma progression." (PMID 18454205, 2008). "Moreover, we also analyzed Hugo cohort (patients with melanoma were treated by PD1 inhibitor) and found patients in non-responding groups had higher VCAN expression than patients in responding group." (PMID 36203562, 2022). "While our IPA analysis did not include the category of melanoma cell migration, RNA-Seq indicated that SDC2 and VCAN might have led to the motility." (PMID 31988291, 2020).
colorectal cancer (24 papers, 2012 to 2025). A primary or metastatic malignant neoplasm that affects the colon or rectum. "Versican and vascular endothelial growth factor expression levels in peritoneal metastases from colorectal cancer are associated with survival after cytoreductive surgery and hyperthermic intraperitoneal chemotherapy." (PMID 33710819, 2021). "VCAN was upregulated in spiky (CRC cell line) that was resistant to growth inhibition of cetuximab, and VCAN staining strongly correlated with reduced survival in colorectal cancer." (PMID 34737677, 2021). "The PPI networks indicate the RAB31, COL1A1, COL1A2, COL3A1, COL11A1, and VCAN as the most important protein network that likely to be connected and show betweenness among themselves to significantly promote the prognosis of colorectal cancer." (PMID 33597969, 2021). "Thirdly, the association between VCAN proteolysis and T-cell inflammation appears to be independent of neoantigen load- VCAN proteolysis predicted T-cell inflammation in both MSI and MSS colorectal cancers." (PMID 29970158, 2018). "In conclusion, we demonstrated for the first time that VCAN is over-expressed in colorectal cancer and VCAN promotes colorectal cancer cell growth in vitro." (PMID 30237752, 2018). "Mukaratirwa and colleagues (2004) observed a significant correlation between stromal immunoreactivity intensity for versican and invasion in colorectal carcinomas in dogs, suggesting that this proteoglycan supports tumour progression." (PMID 23082892, 2012). "Versican proteolysis is associated with increased T-cell infiltration in colorectal cancer independent of mismatch repair status." (PMID 33187209, 2020). "For example, colorectal cancers displaying proteolysis of versican demonstrate enhanced T-lymphocyte infiltration, whilst fragments derived from versican proteolysis (matriknes) promote dendritic cell accumulation, indicating a role for matrikines in the modulation of cancer immunity." (PMID 33187209, 2020). "It is expected that removing versican could suppress its cancer-promoting effect; for example, increasing versican proteolysis enhances the CD8+ T-cell infiltration in colorectal cancer." (PMID 32825245, 2020). "VCAN proteolysis is associated with CTL infiltration in colorectal cancer, regardless of mismatch repair status, and versikine promotes T cell infiltration through regulation of Batf3-DCs." (PMID 29970158, 2018). "CM of all breast and colorectal cancer cell lines enhanced versican and biglycan expression." (PMID 25593993, 2014). "What is noteworthy is that, NCBI GEO gene expression database of TECs in colorectal cancer and lymphoma also verified the specific high expression of 7 out of these 12 ECM associated genes in TECs from colorectal cancer and lymphoma, i.e. SPON2, BMP-1, FN1, POSTN, THBS2, VCAN and AEBP1." (PMID 29541388, 2018). "We recently discovered that an ECM immunomodulatory proteoglycan versican (VCAN) and its ADAMTS-protease proteolytic cleavage product versikine (Vkine) differentially accumulate in the TME of multiple myeloma and colorectal cancers (CRC)." (PMID 40361362, 2025). "For instance, in human colorectal cancer, cleavage of the ECM proteoglycan versican (VCAN) produces versikine, which promotes the differentiation of conventional dendritic cells that enhance T cell-mediated anti-tumor immunity." (PMID 41230456, 2025). "VCAN, an ECM gene was initially downregulated but upregulated in metastasizing cells in the prostate and colorectal cancers." (PMID 32315343, 2020). "Nevertheless, secretome experiments show that nearly all breast and colorectal cancer cell lines induce both α-SMA, versican and biglycan in CAFs, which implies TGF-β1-like effects." (PMID 25593993, 2014).
colorectal cancer (continued). "Versican (VCAN) is a proteoglycan represented by multiple isoforms (V0, V1, V3, V4) that are often overexpressed in the stroma of some solid tumors, including colorectal cancer, pancreatic cancer, and HCC." (PMID 35454809, 2022).
hepatocellular carcinoma (19 papers, 2013 to 2025). A malignant tumor that arises from hepatocytes. "In hepatocellular carcinoma, VCAN exhibits a strong association with immune checkpoint gene expression." (PMID 38980810, 2024). "Versican expression is related to poor prognosis in hepatocellular carcinoma, including increased tumor-associated macrophages(TAMs) infiltration, poor tumor differentiation, and TNM stage." (PMID 37259101, 2023). "Further, VCAN mutation may lead to phenotypic differentiation of hepatocellular carcinoma and cholangiocarcinoma in mixed cancer." (PMID 32311840, 2020). "In hepatocellular carcinoma (HCC), versican (VCAN) secreted by CAFs is associated with malignant transformation and prognosis." (PMID 40038745, 2025). "Our study provides a new anti-hepatoma idea to find some DNA methyltransferase inhibitors and TF inhibitors that can effectively down-regulate the expression of VCAN." (PMID 35812745, 2022). "The results demonstrated that VCAN was downregulated in the hepatocellular carcinoma samples compared with normal samples." (PMID 36407083, 2022). "For example, treating HepG2 hepatocellular carcinoma cells, a cell line that overexpresses c-Src, with vitreous or versican enhanced transgene expression." (PMID 28684419, 2017). "Versican expression increased in the majority of HCC tissues and knocking down of Versican greatly attenuated hepatoma cell invasion." (PMID 27941932, 2016). "Previous relevant studies have shown that VCAN is highly expressed in various malignant tumors, such as kidney cancer hepatocellular carcinoma, and the high expression of VCAN is positively correlated with the high stage, low differentiation, high metastasis rate and poor prognosis of the tumor." (PMID 36842141, 2023). "VCAN is specifically expressed in B cells of hepatocellular carcinoma." (PMID 36407083, 2022). "We used Starbase to mine 20 RBP most likely to interact with VCAN mRNA in hepatoma cell line HepG2." (PMID 35812745, 2022). "Specific extracellular matrix proteoglycans, such as versican, aggrecan, biglycan, and decorin, which are increased in rat hepatocellular carcinomas, may affect binding with the C4S attachments on the proteoglycan." (PMID 27078017, 2016). "Co-treatment with KPA also decreased the expression of genes, regulating the progression of fibrosis (e.g., COL6A3, AEBP1, SPARC, TNC, LAMB1, BGN) and hepatocellular carcinoma (e.g., COL4A1, COL4A2, TUFT1, VCAN, NID1)." (PMID 39404414, 2024). "We then evaluated the expression of SERPINE1, VCAN, and TFPI2 in the hepatocellular carcinoma cohort of the TCGA cohort." (PMID 36407083, 2022). "Then, we evaluated the expression level of SERPINE1, VCAN, and TFPI2 in human hepatocellular carcinoma cells." (PMID 36407083, 2022). "We finally discovered that SERPINE1, VCAN, and TFPI2 play an important role in hepatocellular carcinoma." (PMID 36407083, 2022). "Finally, in order to explore the function of 3 key genes (SERPINE1, VCAN, and TFPI2) in hepatocellular carcinoma patients, we then performed the GSVA enrichment analysis." (PMID 36407083, 2022). "Additionally, we also evaluated the potential function of SERPINE1, VCAN, and TFPI2 in a hepatocellular carcinoma cohort." (PMID 36407083, 2022). "In addition, three glucose metabolism-related genes (SERPINE1, VCAN, and TFPI2) may be the potential targets for the immunotherapy of patients with NAFLD-hepatocellular carcinoma." (PMID 36407083, 2022). "In addition, three glucose metabolism-related genes (SERPINE1, VCAN, and TFPI2) may be potential targets for the immunotherapy of patients with NAFLD-hepatocellular carcinoma." (PMID 36407083, 2022). "In 2013, this group reported that the versican 3′UTR induces the development of hepatocellular carcinoma (HCC) and demonstrated that the versican 3′UTR can increase the expression of versican, CD34, and fibronectin via a ceRNA mechanism in HCC cells." (PMID 26872371, 2016).
atherosclerosis (18 papers, 2010 to 2025). A disease characterized by the build-up of fatty material and calcium deposition in the arterial wall resulting in partial or complete occlusion of the arterial lumen. "Moreover, versican is implicated in many biological processes involving vasculature, such as atherosclerosis and vascular inflammation." (PMID 31263118, 2019). "The authors noted that versican tends to accumulate in human vessels susceptible to atherosclerosis, such as the coronary arteries and the saphenous veins, in comparison to atherosclerosis-resistant vessels, such as the internal mammary and the radial arteries." (PMID 29226146, 2017). "CS is known to interact with apolipoprotein B100 of LDL, leading to retention of LDL in the artery wall and linking increased VCAN to the progression of atherosclerosis." (PMID 40623650, 2025). "The proteomics data also revealed sex differences in atherosclerosis, with large-aggregating proteoglycans versican and aggrecan being more abundant in females and exhibiting an inverse correlation with estradiol levels." (PMID 37646165, 2023). "It is known that the degradation of versican by ADAMTSs is important in the pathogenesis of atherosclerosis." (PMID 37252704, 2023). "The degradation of versican by ADAMTS endopeptidases is known to be important in the pathogenesis of atherosclerosis." (PMID 37252704, 2023). "Reports have highlighted the role of versican in wound healing and in vascular disease, especially atherosclerosis." (PMID 35598150, 2022). "Our group highlighted the importance of ADAMTS‐5 in a mouse model of atherosclerosis 44: lower levels of ADAMTS‐5 accompanied accumulation of versican in aortas of apolipoprotein (apo)E‐knockout mice." (PMID 26940365, 2016). "Versican, an abundant and widely expressed extracellular matrix proteoglycan, has important roles in a number of pathological conditions including cancer and atherosclerosis, in which accumulation of macrophages in hypoxic sites is a feature." (PMID 26057378, 2015). "Several reports have also highlighted the role of versican in wound healing and in vascular disease, especially atherosclerosis." (PMID 26057378, 2015). "Versican is involved in many physiologic and pathologic processes, including neuronal development, atherosclerosis, and the invasive and metastatic signatures of many cancers." (PMID 23845159, 2013). "Concerning proteoglycan expression in the neointima, both perlecan and versican have been shown to be present in neointimal lesions formed after experimental or human stenting or denudation or related to atherosclerosis." (PMID 20140097, 2010). "Increased levels of versican have been reported in diseases such as atherosclerosis and cancers." (PMID 24950767, 2014). "In this regard, recent observations have shown that the initial entrapment of LDL within the extracellular matrix depends on interaction of LDL with biglycan and versican and atherosclerosis-prone arteries, such as the coronary artery, have a thickened intima enriched in versican and biglycan." (PMID 24358251, 2013). "An in vitro study of rat arterial smooth muscle cells showed that overexpression of the Versican V3 subtype significantly reduced the infiltration of macrophages and inhibited the filling of lipids, which showed that Versican V3 subtype played an anti-inflammatory role in atherosclerosis." (PMID 38685004, 2024). "VCAN has previously been studied extensively in vascular smooth muscle cells in relation to atherosclerosis but not in ECs." (PMID 40623650, 2025). "Versican is an important large aggregating PG in the vessel wall, not least due to its involvement in the retention of lipoproteins and development of atherosclerosis (reviewed by Wight and Merrilees 24)." (PMID 26940365, 2016).